IFNG (interferon gamma)
Diseases named in the same sentence as IFNG in open-access papers (continued):
Sharing a sentence is not in itself a finding about the gene and the disease.
cancer (continued). "Similarly, Th1 cells secrete a high level of interferon gamma (IFN-γ) that stimulates the immune response to protect against cancer cells." (PMID 35740686, 2022). "IFNγ contributes to recruitment of T lymphocytes, activates TILs by promoting dendritic cell-mediated antigen presentation, and directly induces apoptosis of cancer cells." (PMID 35053427, 2022). "We finally analyzed transcriptome profiles of ICI-treated patients and associated their response with high levels of IFNγ, Merck18, CD274, CD8, and low levels of myeloid-derived suppressor cells (MDSCs), cancer-associated fibroblasts (CAFs) and M2 macrophages, irrespective of their TMB status." (PMID 36389735, 2022). "The combination treatment-induced systemic immune response was evaluated by measuring the secretion of serum proinflammatory cytokines with ELISA assay, including tumor necrosis factor-alpha (TNF-α), interferon-gamma (IFN-γ) and interleukin-6 (IL-6), that play vital roles in anti-cancer immunity." (PMID 35812418, 2022). "Preliminary studies have found that activation of cell signaling pathways such as the interferon-gamma (IFNγ) pathway confers resistance to ICB, however the underlying mechanisms of unresponsiveness to ICB in various types of cancers are still poorly understood." (PMID 35372044, 2022). "However, accumulating evidence suggests dual effects wherein IFNγ signaling promotes cancer development and immune evasion." (PMID 34385592, 2022). "In GSEA analysis based on hallmarks geneset, CDKN2B-AS1 may be involved in the activation or shutdown of many cancer classic pathways, such as epithelial mesenchymal transition, allograft rejection, interferon gamma response, and inflammatory response." (PMID 35432631, 2022). "Overall, we found that the TR-DDR score had positive correlations with the expression of PDL1, and IFNG in over ten cancers, suggesting that these signatures may play more roles in the crossroads of the DDR pathway and immune response." (PMID 36081518, 2022). "Intracerebral (Z)-BP in residual tumors could not only inhibit cancer stem cells but also increase interferon gamma levels in serum, which then led to the regression of GBM and an immune-responsive microenvironment." (PMID 35646111, 2022). "The induction of ICD should stimulate an anti‐cancer immune response, and interestingly, we see dynamic changes in immunological pathways, such as interferon gamma (IFN‐γ) and alpha (IFN‐α), with an increase on Day 10 (IFN‐γ: NES = 1.62, FDR = 0.008; IFN‐α: NES = 1.70, FDR = 0.004)." (PMID 36176603, 2022). "Moreover, IFNγ can exert a direct anticancer effect on cell proliferation and induce cancer cell apoptosis and necroptosis." (PMID 34385592, 2022). "Interestingly, while all cancer cell lines showed evidence of lower membranous E-cadherin expression after IFNγ treatment, statistical significance was only achieved for PC3-H, DU-L and DU-H cells and no change was noticed in RWPE cells." (PMID 35459800, 2022). "Previous pre-clinical and clinical studies using macrophages as a therapeutic strategy to combat cancer have shown that the function of macrophages generated ex vivo is enhanced through pre-stimulation with LPS or IFNγ prior to adoptive transfer into the patient." (PMID 35326445, 2022). "These analyses revealed that while treatment with arachidonic acid (AA, a 20-carbon chain PUFA with four double bonds; C20:4) alone triggers little ferroptosis, AA synergizes with IFNγ to induce potent ferroptosis in diverse cancer cell lines in an ACSL4-dependent manner." (PMID 35459217, 2022). "What connects IFNγ signaling and type I PRMTs in cancer persistence?" (PMID 35089788, 2022). "When ovalbumin-expressing cancer cells were cocultured with OT-I T cells, we observed that OT-I T cells were able to kill more sgSlc4a4 cells than sgNT cancer cells (control), together with an increase in cytotoxicity markers such as IFNγ and granzyme B (GZMB)." (PMID 36522548, 2022).
cancer (continued). "Although, in most cancer types, IFNγ exerts strong anti-tumorigenic effects, several lines of evidence suggest that the increased production of IFNγ during TKI treatment might play a negative effect on the therapeutic response of CML patients." (PMID 35979386, 2022). "At low levels, IFNγ induces cancer cell stemness resulting in increased metastasis." (PMID 35712656, 2022). "Overall, these findings indicate that the activation of IFNG may lead to therapeutic effects in cancers such as BC and AML." (PMID 35758779, 2022). "Moreover, IFNγ-induced W>F substitutants add a new layer to the landscape of the immunopeptidome presented on cancer cells." (PMID 35264796, 2022). "Hence, we focused on the regulation of the IFNγ signaling pathway at the epigenetic, transcriptional, posttranscriptional, and posttranslational levels in the context of cancer immunity." (PMID 34385592, 2022). "Besides, the low-risk group had higher interferon gamma (IFNG), higher microsatellite instability (MSI) score, and lower cancer-associated fibroblasts (CAFs) amount, which confirmed the more activated immune landscape in this subgroup." (PMID 35495147, 2022). "Further studies may be directed to elucidating molecular mechanisms and benefits of CQ modulation of IFNγ expression in normal skin cells, immune cells, and cancer cells." (PMID 35847840, 2022). "Echoing what we observed using broad immune phenotypes, IFNγ-producing cytotoxic CD8 (P1_47), as well as CD14 + monocytes (P2_31), were deficient in cancer compared to healthy immunomes." (PMID 36307410, 2022). "Some of the significant cancer hallmark terms are inflammatory response (CD14, CD69, IL10RA), KRAS signaling up (CD37, IL10RA, GPNMB), IL-6/JAK/STAT3 signaling (CD14, CSF2RB), Interferon Gamma Response (CD69, CSF2RB, IL10RA, VCAM1, SLAMF7), TNF-alpha Signaling via NF-kB (CD69)." (PMID 35486660, 2022). "Similarly, at high levels of IFNγ in inducible models producing ∼10 ng per ml, IFNγ acts on stromal cells independently of cancer cells to induce vascular regression and eliminate blood flow to tumors." (PMID 35712656, 2022). "Of note, both the upregulation of PD-L1 and the promotion of ferroptosis were driven by CD8+ T cells released IFNγ, which foreshowed that T cell-mediated ferroptosis might be involved with the phenotypic alteration in cancer cells." (PMID 35874826, 2022). "Moreover, blockade of IFNγ signaling suppresses the expression of ISGs (common biomarkers for ICB response) in cancer cells while increases ISGs in immune cells." (PMID 36142818, 2022). "For GSVA results of 50 hallmark pathways from the MSigDB, we found that FUCA2 was associated with many cancer-promoting and immune-related pathway, including Glycolysis, PI3K AKT MTOR signaling, TGF BETA signaling, interferon alpha and interferon gamma response in pan-cancer." (PMID 34745134, 2021). "However, upon CD40 costimulation, macrophages secrete NO, IL-12, and IFNγ, which are characteristic for proinflammatory M1-like activation state that leads to apoptotic-destruction of cancer cells in vitro and in vivo independent on T cell activity." (PMID 33919517, 2021). "Genes in green are engaged in interferon-gamma signaling that has dual roles in cancer." (PMID 34249670, 2021). "Inhibition of GFAT in IFNγ-treated cancer cells was found to inhibit PD-L1 glycosylation, accelerating its proteasomal degradation and, more importantly, enhancing T cell activation and anti-cancer activity of natural killer cells." (PMID 35223460, 2021). "Therefore, IFNγ‐induced increase in the expression of MHC class I molecules is a suitable strategy for cancer cells to escape from NK cells." (PMID 33491334, 2021). "As already described in murine and human memory-like NK cells, we documented that the majority of memory-like NK cells derived from both haplo-HSCT donors and cancer patients were able to secrete IFNγ compared with the low percentage present in control NK cells." (PMID 33808051, 2021).
cancer (continued). "Here, by using T cell bispecific antibodies and chimeric antigen receptors (CAR) T cells targeting HER2, the authors show that cancer cell intrinsic disruption of interferon-gamma signalling, including downregulation of JAK2, confers resistance to T-cell mediated cytotoxicity." (PMID 33623012, 2021). "M1-like TAMs can eliminate cancer cells by driving T cell proliferation (both cytotoxic T lymphocytes and T helper 1 cells), secreting the toxic molecule nitric oxide (NO) and pro-inflammatory cytokines (e.g., IFNγ, IL-1β, IL-12, and TNFα)." (PMID 34829860, 2021). "Additionally, IFNγ was shown to induce macrophages to produce nitric oxide and increase direct lysis of cancer cells." (PMID 33801234, 2021). "However, it was demonstrated that IFNγ from lymphocytes induces PD-L1 expression and promotes the progression of cancer." (PMID 34572311, 2021). "Indeed, NK cells infiltrating several cancers, including gastric cancer and hepatocellular carcinoma, showed reduced IFNγ and TNFα production as well as reduced proliferation and cytotoxicity compared to NK cells from healthy tissues." (PMID 34203391, 2021). "Moreover, a previous study has identified the IFNG gene signature and IFNG expand gene signature for characterizing the IFNG response based on pan-cancer analysis." (PMID 34566988, 2021). "Importantly, IFNγ‐induced PD‐L1 is one of the major mechanisms by which cancer cells escape host immunity." (PMID 33491334, 2021). "Inflammatory macrophages play an important role in cancer initiation by creating a mutagenic micro-environment through producing proinflammatory mediators, such as IL-6, TNFα, and interferon-gamma (IFNγ); as well as growth factors, including epidermal growth factor (EGF) and metabolites." (PMID 34207286, 2021). "We expected that nitric oxide (NO) produced by activated macrophages would inhibit the growth of 4T1/eGFP spheroids; furthermore, IFNg was shown to have a direct antiproliferative effect on cancer cells, providing strong evidence of spheroid inhibition in the presence of M1 and vdIFNg." (PMID 34835178, 2021). "Nevertheless, the beneficial antitumor effect of SFV/IFNg shown in this study may contribute to establishing promising immunotherapies for cancer in the future." (PMID 34835178, 2021). "The CD8 T cell-dependent killing of cancer cells could produce interferon-gamma (IFN-γ) and then activate antitumor immunity." (PMID 34970479, 2021). "Additionally, it is well-established that IFNγ upregulates PD-L1 expression to promote cancer immune resistance." (PMID 34479614, 2021). "The process of thrombopoietin signaling and cancer immunoediting might rely upon a variety of cytokines such as interferon gamma and cell types such as NK cell, which could be affected by JAK inhibition." (PMID 35087406, 2021). "Indeed, PGE2, by acting on EP2 and EP4 on NK cells, impaired their capability to release IFNγ and thus to maintain a cancer inhibitory microenvironment." (PMID 34203391, 2021). "IFNγ is a potent activator of Th1 anti-cancer immune responses." (PMID 33244152, 2020). "In fact, IFNγ can prevent the development of malignant tumors and metastases." (PMID 32326210, 2020). "T-cells can then produce interferon gamma (IFN-γ) to induce cytolysis in cancer cells." (PMID 32656079, 2020). "Cancer cells, tumour-associated stromal cells, and activated T-cells play a role in initiating these signalling pathways involved in MDSC activation via the expression of TLR4, IL-1β, TGFβ, IFNγ and IL-4." (PMID 32121014, 2020). "For instance, immune system could induce tryptophan degradation to inhibit the growth of certain cancer cells via interferon gamma (IFN-γ) upregulating the tryptophan-catabolizing activity of indoleamine 2,3-dioxygenase (IDO)." (PMID 32190097, 2020). "Hence, cytokines like IFNγ and TNFα can play dual roles in cancer progression and the internal complexity of combined receptor signaling strongly affects antitumor responses." (PMID 32733461, 2020).
cancer (continued). "In order to discern whether these cells were having an impact on NK cell cytokine production, we quantified the percentage of CD14−FSC-AhiSSC-Ahi cells and plotted this against intracellular IFNγ in the same 11 healthy donors and nine cancer patients." (PMID 32508837, 2020). "Although, IFNγ is a dominant driver of PD-L1 expression in various tumors, the mechanism by which IFNγ mediates PD-L1 upregulation appears to be distinct among different cancer types." (PMID 33193345, 2020). "In addition, extracellular IFNγ was quantified in 13 healthy donors and 10 cancer patients from plasma collected prior to intracellular staining." (PMID 32508837, 2020). "However, in some types of cancers, PD-L1 is reported to be expressed on the surface of cancer cells by means of stimulation from interferon gamma (IFNγ), a proinflammatory cytokine." (PMID 31914969, 2020). "As a consequence, the increase in the number of TILs, with high ratio CD8+/Treg, and activated CD8+, may elicit a direct cytotoxic response to eradicate cancer cells, through the generation of IFNg, perforin-1, and granzyme B." (PMID 33574894, 2020). "In addition to these clones, a sizeable portion of short-term expanded NY-ESO-1-specific and SSX-2-specific CTL lines from two other cancer patients exhibited hypermethylation of their IFNγ gene promoter." (PMID 32451453, 2020). "Indeed, early studies on IFNγ and cancer biology established its role as an antitumor cytokine; however, now it is known that this cytokine can have a dual role in shaping the outcome of cancer." (PMID 32937860, 2020). "Likewise, induction of IDO1 by inflammatory cytokines, including IFNγ and tumor necrosis factor α (TNF-α), has been linked to poor prognosis in CMM as well as various different cancer types." (PMID 32117720, 2020). "When attacked by cytotoxic T lymphocytes, cancer cells are able to utilize IFNG in TIME to activate their own signaling pathway related to signal transducers and activators of transcription (STATs), which in turn upregulates PD-L1 expression and suppresses incoming immune attacks." (PMID 33299118, 2020). "Cancer cells are able to secrete proinflammatory factors (TNFα, IFNγ, IL6, etc.)that enhance the recruitment of immune cells to the inflammation site, including polymorphonuclear neutrophils and eosinophils, monocytes, lymphocytes, natural killer cells (NK), and mature dendritic cells." (PMID 32752264, 2020). "IFNγ has been shown to induce PD-L1 expression in various cancers." (PMID 34212113, 2020). "According to several studies that have reported the role of soluble checkpoint molecules in the promotion and progression of cancer, downregulating immune activation, here we demonstrated that IFNγ, sPDL1 and sCTLA4 play important roles in regulating the response to TKI treatment." (PMID 32937860, 2020). "Macrophages can differentiate into M1 macrophages in the presence of lipopolysaccharide (LPS) and interferon gamma (IFNγ), release a series of cytokines, result in the low expression of interleukin (IL-10) and high expression of IL-12, and inhibit and kill cancer cells." (PMID 31186031, 2019). "Interestingly, preventing cancer cell IFNγ signaling had a much more variable effect than removing negative feedback on the pathway, promoting resistance or sensitization to NK cells in target and effector cell dependent manner." (PMID 31452512, 2019). "We hypothesized that intrinsic differences in the responsiveness of cancer cells to IFNγ, distinct from other features of these cells, define the nature of the TME and control sensitivity of lung tumors to immunotherapy." (PMID 31133614, 2019). "Moreover, crizotinib favored the infiltration of cancers by interferon-γ (IFNγ)-producing T lymphocytes in urethane-induced NSCLC." (PMID 30940805, 2019). "Moreover, IFNγ is an anticancer cytokine that suppresses the progression and metastasis of cancer cells, including 4T1 cells." (PMID 30814922, 2019).
cancer (continued). "Notably, CXCL9, CXCL10, and IFNG had significantly higher expression levels in the higher-TMB subtype of at least 10 cancer types, while had significantly higher expression levels in the lower-TMB subtype of at most 4 cancer types." (PMID 30634925, 2019). "In this study we report that the therapeutic treatment with MET inhibitors, in addition to the intended direct antitumour activity against MET-driven cancers, provides a bystander effect revoking the IFNγ-induction of PD-L1/PD-L2 through the inhibition of JAK-STAT pathway." (PMID 30723303, 2019). "TIGS also shows improved performance in ICI clinical response prediction when compared with TMB and other biomarkers that are based on gene expression profiling (TIDE, interferon gamma signature and so on) in both prediction accuracy and pan-cancer applicability." (PMID 31767055, 2019). "This marker can thus be used to predict the outcome of the disease and in combination with T cell functional markers such as IL2, TNFα, and IFNγ could predict patient's response to specific cancer vaccine." (PMID 30740111, 2018). "IFNγ-induced PD-L1 expression has a unique histopathological pattern, which is usually focal rather than diffuse and is expressed in cells adjacent to TILs, as observed in most human cancers." (PMID 30409126, 2018). "In addition, TNFα can directly kill tumors expressing TNFRs and works in concert with IFNγ to inhibit cancer cell proliferation." (PMID 30400618, 2018). "Moreover, IFNγ signaling is a crucial pathway in the resistance to anti-PD-1 therapy in patients with cancer." (PMID 29764444, 2018). "In contrast, the up-regulated genes were significantly implicated in several cancer hallmark-related activities, including epithelial-mesenchymal transition (EMT), interferon gamma response, up-regulation of the KRAS signaling pathway, hypoxia, and TNFA signaling mediated by NF-κB." (PMID 30240750, 2018). "Earlier clinical studies involving patients with advanced cancer indicate that reduced or impaired IFNγ signaling may negatively affect patient survival." (PMID 29970101, 2018). "Intriguingly, cancer prone mutations in SAMHD1, which is required for replication fork stability and regulation of Mre11-dependent degradation of nascent DNA, activate the IFNγ pathway promoting cancer development." (PMID 29950452, 2018). "However, IFNγ also contributes to the subsequent cancer evasion by promoting tumorigenesis and angiogenesis, eliciting expression of tolerant molecules and inducing homeostasis program." (PMID 30039553, 2018). "PD-1 blocker-based therapy ultimately depends on CD8+ T cells and IFNγ for cancer eradication." (PMID 30577797, 2018). "IFNG encodes for interferon-γ (IFN-γ), also known as type II interferon, a pro-inflammatory cytokine that participates in the regulation of both innate and adaptive immunity against pathogens or cancer cells." (PMID 30337874, 2018). "In respond to IFNγ, cancer cells express PD-L1 to launch a feedback inhibition on T cells." (PMID 30062558, 2018). "Pegilodecakin treatment induced the hallmarks of CD8+ T-cell immunity in cancer patients, including the systemic elevation of IFNg and GranzymeB levels, expansion and activation of CD8+ TILs, invigoration and expansion of PD-1+/Lag-3+ CD8+ T-cell sub-set and the de-novo expansion of T-cell clones." (PMID 30400835, 2018). "When the cells were treated with a combination of cetuximab and MEK or JNK, the expression levels of CCL5, CXCL9 and CXCL10 increased, confirming that not one but multiple pathways downstream of the EGFR act in concert to block IFNγ/TNFα -induced chemokine expression by these cancer cell lines." (PMID 30192802, 2018).